IFNG (interferon gamma)
Diseases named in the same sentence as IFNG in open-access papers (continued):
Sharing a sentence is not in itself a finding about the gene and the disease.
COVID-19 (continued). "Subtraction of IFNγ values obtained after stimulation with DMSO in the absence of MPs showed significantly increased levels of IFNγ production induced by MP_R and MP_S in OTD-CoV-2pos compared with OTD-CoV-2neg subjects and severe COVID-19 patients." (PMID 34858405, 2021). "The proportions of IFNγ+CD4+ and IFNγ+CD8+ T cells and the titers of IgG, IgM, and IgA against SARS-CoV-2 spike protein increased and inversely correlated with the SARS-Cov-2 viral load in surviving hypertensive patients with severe COVID-19." (PMID 33362779, 2020). "Because IFNs play a central role in viral immune responses, and our monocyte transcriptome data from COVID-19 patients revealed enhanced IFN-stimulated gene expression, we investigated how inflammatory monocytes respond to restimulation with IFNα, IFNβ, and IFNγ." (PMID 33377122, 2020). "We characterized the ex vivo ability of different leukocyte subsets of patients admitted to the hospital with COVID-19 to produce GrB, perforin, tumor necrosis factor (TNF-α) and interferon-gamma (IFN-γ) after short-term ex vivo stimulation with phorbol myristate acetate (PMA)/ionomycin." (PMID 32707842, 2020). "In the context of COVID-19, kefir demonstrated antimicrobial and immunomodulatory activity by downregulating the expression of pro-inflammatory cytokines such as interleukin-6 (IL-6), interleukin-1 (IL-1), tumor necrosis factor-alpha (TNF-α), and interferon-gamma (IFN-γ)." (PMID 40647113, 2025). "Studies on severe COVID-19 cases reported exhaustion of T-cells, high expression levels of programmed cell death protein 1 (PD-1), T-cell immunoglobulin and mucin domain 3 (Tim-3), and NKG2A along with the diminished expression of T-cell activation markers CD107, and interferon gamma (IFN-γ)." (PMID 38965547, 2024). "Thus, the weakened IFNγ response to SARS-CoV-2 and elevated levels of immunosuppressive IL-10 in both COVID-19 and dengue during the early phase of illness indicates an inadequate antiviral response that could contribute to the severity of the diseases." (PMID 39519178, 2024). "They hypothesized that increased interferon gamma expression in CD4+ T cells, which has been reported to play a central role in COVID-19-related cytokine storms, may have triggered the activation of adaptive immune responses and initiated the formation of sarcoidal granulomas." (PMID 39403183, 2024). "We found that the TLR-7 agonist, Resiquimod, and the TLR-4 ligand, LPS, induced significantly better IFNα and IFNγ responses in the later phase (day 28) of SARS-CoV-2 infection in those non-hospitalized COVID-19+ individuals as compared to early infection (day 0 and day 7)." (PMID 38543837, 2024). "Interleukin (IL) 2 and 6 (IL-2, IL-6), tumor necrosis factor-alpha (TNF-α), interferon-gamma (IFN-γ), macrophage inflammatory protein (MIP), and monocyte chemoattractant protein 1 (MCP-1) are among many other cytokines that are present in seriously ill COVID-19 patients." (PMID 36901751, 2023). "Nevertheless, another study showed that in paediatric/young COVID-19 patients (n = 65, < 24 years) who generally suffer less severe disease there were increased serum levels of IFNγ and IL-17A but not of IL-6 and TNFα protein compared to adult COVID-19 patients (n = 65)." (PMID 36941580, 2023). "By contrast, IFNγ was reduced with COVID-19 in non-pregnant individuals but not pregnant patients." (PMID 37016066, 2023). "The elevation of IL-7, granulocyte-macrophage colony stimulating factor, interferon-gamma (IFN-γ), and fibroblast growth factor in COVID-19 patients might be involved in the development of AKI in COVID-19 patients and induced endothelial cell and tubular dysfunction." (PMID 37533739, 2023). "The severe COVID-19 patients responded well to IFNγ without adverse events." (PMID 37359519, 2023).
COVID-19 (continued). "In fact, from the group comparison of COVID-19 vs. non-COVID-19, the authors identified 14 specific inflammatory proteins that can be related to SARS-CoV-2 infection, namely CXCL5, CXCL10, CXCL11, Gal-9, IL-18, IL-18R1, IFNγ, LIF-R, MCP-2, MCP-3, MERTK, MMP-1, PD-L1, and TNF." (PMID 35269564, 2022). "Moreover, IFNγ was not increased in patients with COVID-19 whereas TNFα levels were lower in COVID-19 patients than in patients with sepsis and CAR-T cell-induced CRS." (PMID 36158866, 2022). "Moreover, patients with COVID-19 had significantly less central and effector memory CD4 T-cell subsets capable of IFNγ and TNFα co-expression in response to a polyclonal in vitro stimulation with PMA/Ionomycin mixture in comparison with the controls and COVID-19 convalescents." (PMID 35632823, 2022). "Notably, all close contacts developed responses at lower frequencies than 4%, while 64 (71.11%) and 32 (35.56%) of the 90 COVID-19 patients developed marked responses at the frequencies of higher than 4% for IFNγ+CD4+ T cells and IFNγ+CD8+ T cells, respectively." (PMID 33741972, 2021). "Emapalumab (anti-IFNγ) is FDA-approved for HLH and may be effective in COVID-19 inflammatory phase." (PMID 33495742, 2021). "In a recent study we showed that COVID-19 patients generate a large number of polyfunctional antigen-specific T cells, expressing at least two of the pro-inflammatory Th1 cytokines TNF, IL-2, IFNγ or the cytotoxic granzyme B, after stimulation with M, N or S OPPs." (PMID 34228322, 2021). "PIMS-TS children had significantly elevated levels of cytokines, IFNγ, IL-2, TNFα, IL-1α, IFNα, IFNβ, IL-6, IL-15, IL-17A, GM-CSF, IL-10, IL-33 and IL-Ra; elevated chemokines, CCL2, CCL19, CCL20 and CXCL10 and elevated VEGF, Granzyme B and PDL-1 in comparison to COVID-19, seropositive and controls." (PMID 33813138, 2021). "In this regard, interferon-gamma release assays (IGRAs), such as the QuantiFERON-TB Gold Plus (QFT-Plus; Qiagen, Germany) assay, have been unsystematically performed for LTBI screening in some severe COVID-19 patients, before or during immunosuppressive therapy." (PMID 33652893, 2021). "The latest report indicates the infection of SARS-CoV-2 increases the expression levels of multiple proinflammatory cytokines, including interferon-gamma (IFN-γ), TNF-α, CCL2, and IL-6 in the serum, which suggests the inflammation storm may be involved in pulmonary inflammation in COVID-19." (PMID 32418550, 2020). "IFNγ serum levels in SARS-CoV-2 infected patients are also closely related to the development of clinical symptoms, causing flu-like symptoms as general malaise, headaches, fever and fatigue, but increased serum INFγ levels is usually correlated to non-severe COVID-19." (PMID 36941580, 2023). "Among the 19 patients who experienced COVID-19 during the vaccine cycle, 5 (26.3%) were not responders at the humoral level (i.e., they did not develop IgG), while only one patient did not respond at the cellular level (i.e., he did not develop an IFNγ response)." (PMID 37705978, 2023). "Together, our data show that a pre-established IFNγ response within the lung is protective against SARS-CoV-2 infection, suggesting that concurrent or recent infections that drive IFNγ may limit the pathogenesis of SARS-CoV-2 and supporting possible prophylactic uses of IFNγ in COVID-19 management." (PMID 38086794, 2023). "With regard to the analysis of IFNγ levels in COVID-19 patients, transcript amounts for IFNγ were reduced in the lower respiratory tracts and PBMCs of critically ill patients compared to healthy donors despite all patients had negative results for plasma anti-IFNγ autoantibody detection." (PMID 36985262, 2023). "Moreover, symptomatic children with COVID-19 were found to have higher viral load, lower total lymphocyte count, lower lymphocyte subsets, and elevated interleukin 6 (IL-6), IL-10, tumor necrosis factor-alpha (TNF-α), and interferon-gamma (IFN-γ) levels compared with asymptomatic patients." (PMID 34975908, 2021).
COVID-19 (continued). "Conversely, serum levels of IFNG and IL12B were significantly lower in severe COVID-19 among SOT recipients, but not among controls." (PMID 39794319, 2025). "We determined that increased interleukin (IL)-6 and IL-10, and tumor necrosis factor-α and interferon gamma were not predictive of severe ANE and mortality in children with COVID-19 in this study." (PMID 37602239, 2023). "Despite also driving strong IFNγ responses in humans, Mtb-infected individuals are not protected from SARS-CoV-2 and if anything, appear to show increased COVID-19 disease." (PMID 38086794, 2023). "This included IFNα1 and IFNβ1 (respectively), IFN-II, such as IFNγ (respectively), and IFN-III, except for IFNλ1, which was expressed in COVID-derived PBMCs from critical COVID-19 patients, but not in COVID-derived monocytes." (PMID 37310504, 2023). "Considering the Mitogen-Nil condition of the QFT-Plus, an impaired production of interferon-gamma (IFN-γ) was found in non-survivors (p < 0.001) and in severe COVID-19 patients (p < 0.001)." (PMID 35207531, 2022). "Similarly, to evaluate the impact of the booster on the cellular response, IFNγ concentration levels before and 21 days after administration of the third vaccine dose were compared between two cohorts: participants with and without a prior positive history of COVID-19 before the study started." (PMID 36146624, 2022). "We investigated the circulating levels of IFNγ, IL-4, sIL-4R, IL-5, IL-9, IL-17A, IL-17F, IL17-E/25, IL-22 and sCD30 in surviving and non-surviving severe COVID-19 patients and healthy controls." (PMID 36142255, 2022). "We also noted that, in the COVID-19-naive population, the frequency of AIM+IL-2+CD8+ T cells (but not IFNγ+ or TNFα+CD8+ T cells) was greater among the older subjects compared with the young group." (PMID 34868051, 2021). "Our data further demonstrated a smoking-induced increase in serum furin and inflammatory cytokine [IFNγ(p = 0.0836), Eotaxin (p < 0.05), MCP-1 (p < 0.05), and IL-9 (p = 0.0991)] levels in COVID-19 patients as compared to non-smoking controls." (PMID 34122129, 2021). "We also noted that, in the COVID-19-naive population, the frequency of AIM+IL-2+CD8+ T cells was greater among the older than among the younger, but frequencies of IFNγ+, TNFα+, or triple+ CD8+ T cells were not different." (PMID 34868051, 2021). "Our data showed that the proportions of IFNγ+CD4+ and IFNγ+CD8+ T cells increased and inversely correlated with SARS-CoV-2 viral load in surviving hypertensive patients with severe COVID-19 but not in the fatal cases." (PMID 33362779, 2020). "Instead, we tested the predictive power of age, gender and BMI on COVID-19-related complications, but apart from plasma IL6 levels and stimulated IFNγ levels the other variables remained non-significant at multivariable analysis." (PMID 33585507, 2020). "Furthermore, IFNG (IFN-γ gene) was specifically increased in the Malawian cohort in CD4 and CD8 T cells versus HLCA COVID-19 and non-LRTD groups." (PMID 39567718, 2024). "We did not observe changes in IFN-I (IFNα and IFNβ), IFN-II (IFNγ), or IFN-III (IFNλ1) mRNA levels in COVID-derived PBMCs or monocytes, except for IFNλ1, which was significantly increased in PBMCs from patients with critical COVID-19." (PMID 37310504, 2023). "However, the effects of IFNL4, ACE1, PKR, IFNG, and MBL2 in severe COVID-19 have not been systematically assessed." (PMID 35623072, 2022). "We found for CD4+ T cells, COVID-19 plasma exosomes obtained from patients upon admission stimulated production of IL-6, IL-8, and TNF-α compared to plasma exosomes from non-COVID donors, with expression of IFNγ not being significantly affected." (PMID 36526691, 2022).
COVID-19 (continued). "After stimulation with controls and peptide pools spanning SARS-CoV-2 wt and Delta spike proteins, interferon gamma (IFN-γ) and interleukin 2 (IL-2) mRNA levels in total cellular RNAs were measured with RT-qPCR from PBMC samples of 15 vaccinees, 10 COVID-19 patients, and 10 negative controls." (PMID 35529867, 2022). "The circulating level of IFNγ is higher in both severe and mild COVID-19 patients while transforming growth factor (TGF)β in severe COVID-19 patients is significantly higher than that in mild COVID-19 patients and negative controls." (PMID 34281182, 2021). "Furthermore, we also did not see any difference between severe COVID-19 and moderate COVID-19 patients in the proportion of SARS-Co-V2-specific IFNγ-producing CD4+ or CD8+ T cells expanded in vitro (p = 0.71 for CD4+, p = 0.48 for CD8+)." (PMID 33741972, 2021). "In addition to these three markers, the ICU group tend to be separated from non-ICU patients by OSM and S100A12, whereas all COVID-19 patients can be distinguished from healthy controls by CASP8, IFNγ, IL-18R and CCL8." (PMID 33239683, 2020). "We found that plasma exosomes from COVID-19 patients significantly induced the production of the same set of cytokines and chemokines that contribute to the severity of COVID-1949–53, including IL-6, IL-8, TNF-α, IFNγ, CCL1, and GDF-15, in PBMCs compared with those from non-COVID donors." (PMID 36526691, 2022). "This provides evidence that MLKL activation in COVID-19 may not occur downstream of activated RIPK1–RIPK3 to promote necroptosis, but rather by alternative RIPK3-independent inflammatory responses such as via IFNγ as previously reported in inflammatory arthritis." (PMID 35244141, 2022).
melanoma (1,405 papers, 1988 to 2026). A malignant, usually aggressive tumor composed of atypical, neoplastic melanocytes. "SOX10 deficiency sensitizes melanoma cells to pyroptosis induced by TNFα and IFNγ, triggering caspase-dependent mechanisms that enhance ICD." (PMID 41235238, 2025). "Previous studies exploring melanoma cell–NK‐cell interactions revealed the development of a protective phenotype of melanoma cells, showing less susceptibility to NK‐cell‐mediated killing (NKmK), which was mediated through IFNγ signaling." (PMID 41078003, 2025). "To examine the role of IFNγ in melanoma susceptibility to NKmK within a more physiologically relevant context, we adapted the 2D in vitro cytotoxicity assay to a 3D spheroid model." (PMID 41078003, 2025). "Our findings indicate a positive correlation between tumor‐intrinsic IL4I1 expression and the expression of HLA‐A/‐B/‐C, B2M, and genes associated with CTL activation (GZMB, GZMA, CD8A, IFNG) in melanoma patients." (PMID 40583248, 2025). "Mechanistically, high levels of ULK1 are associated with the interferon-gamma (IFN-γ)-induced immunosuppressive response of melanoma cells, indicating that a copper chelation strategy can also be considered in melanoma patients treated with ICIs." (PMID 39970778, 2025). "Similar to our findings regarding the melanoma susceptibility to NKmK upon IFNγ exposure, we find the upregulation of MHC II surface expression to be dependent on the initial IFNγ concentration in 1205Lu." (PMID 41078003, 2025). "Here the authors show, by analyzing immune landscape differences between WT and IFNγ receptor-deficient mouse B16-F10 melanoma tumors, that local IFNγ induces complex cellular crosstalk to promote anti-tumor immunity in the latter scenario." (PMID 39746898, 2025). "Our experimental data confirmed IFNγ release during co‐culture and revealed a strong correlation between IFNγ concentration and melanoma cell susceptibility to NKmK." (PMID 41078003, 2025). "In a murine model, studies showed that a reduction in tumor-specific Th17 cells facilitated the advancement of B16 melanoma, with this effect directly associated with the production of IFNγ." (PMID 41019045, 2025). "This supports our findings in the 624Mel cell line and further associates high IFNγ-induced PD-L1 expression with dedifferentiated melanoma cells." (PMID 39736644, 2024). "Defects in IFNγ signaling (which also prevent IFNγ-induced MHC expression) have been identified in 4–10% of PD1-resistant melanomas and are often due to loss-of-function mutations in the IFNγ effector kinases JAK1 and JAK29,16." (PMID 36934113, 2023). "Studies on human melanoma biopsies found an IFNγ signature to be associated with a high response to checkpoint inhibitor therapy in patients, and in vitro exposure of 58 distinct human cell lines to IFNγ induced a similar signature." (PMID 37455828, 2023). "In this experiment also, D10 IFNγ-R1High melanoma cells showed higher IFNγ-dependent susceptibility to T cell killing than IFNγ-R1Low cells." (PMID 35395848, 2022). "Having observed an enhanced sensitivity of STUB1-deficient melanoma cells to cytotoxic T cell-derived IFNγ in vitro, we next investigated the effects of enhanced IFNγ signaling and its relationship to anti-PD-1 treatment in vivo." (PMID 35395848, 2022). "Data from subcutaneous and intraperitoneal models of murine melanoma and lung cancer have revealed a key role for LTα3 and IFNγ signaling in TLS associated HEV formation." (PMID 34568423, 2021). "Expression of B cell-activating factor (BAFF) in human cancers tracked with IFNγ signatures and was positively associated with the overall survival in the TCGA melanoma cohort." (PMID 34201655, 2021). "Analysis of tissue samples from melanoma patients with Ipilimumab-associated colitis revealed IFNγ as the highest expressed inflammatory cytokine in the colonic mucosa of these patients." (PMID 33777008, 2021).